CALR (calreticulin)
Diseases named in the same sentence as CALR in open-access papers (continued):
Sharing a sentence is not in itself a finding about the gene and the disease.
colorectal cancer (25 papers, 2007 to 2026). A primary or metastatic malignant neoplasm that affects the colon or rectum. "In vivo models of B-cell lymphoma and colorectal cancer demonstrated that melphalan causes immunogenic cell death, determined by surface-exposed calreticulin and release of high-mobility group box 1 (HMGB1)." (PMID 41160198, 2025). "Previous studies have shown that a high expression of CALR has been linked with improved outcomes in some carcinomas, such as colorectal carcinoma, NSCLC, AML, osteosarcoma, glioblastoma, and ovarian carcinoma." (PMID 36338983, 2022). "For example, mutations in gene CALR were reported to cause breast and colorectal cancer, ovarian carcinoma, and prostate cancer, and the mutations reported were missense mutations." (PMID 33836673, 2021). "Previous studies have shown that CALR is associated with various diseases, such as myeloproliferative neoplasms (MPNs), neuroblastoma, colorectal carcinoma, non-small cell lung carcinoma (NSCLC), acute myeloid leukemia (AML), osteosarcoma, and glioblastoma." (PMID 36338983, 2022). "Additionally, CALR is clinically associated with high survival rates in colorectal cancer patients, indicating that a combination of NTMT1 protein degradation drugs and immune checkpoint therapy may improve the efficacy of tumor treatment." (PMID 37901469, 2023). "miR-27a downregulated HLA class I surface expression through the suppression of calreticulin in colorectal cancer cells." (PMID 38539461, 2024). "The miR-27a- calreticulin axis affects drug-induced immunogenic cell death in human colorectal cancer cells." (PMID 29137318, 2017). "We have discovered novel mutations in the antigen presenting machinery genes; Tapasin, Erp57, Calreticulin and Calnexin in colorectal cancer." (PMID 17316446, 2007). "Oxaliplatin but not cisplatin was shown to trigger immunogenic cell death of colorectal cancer cells, activated dendritic cells by expressing danger signals such as heat shock proteins, calreticulin, HMGB1, and efficiently generated a pool of tumor antigen-specific T cells." (PMID 36899361, 2023). "For example, researchers found that miR-27a could affect drug-induced apoptosis of human colorectal cancer cells through targeting CALR." (PMID 33209200, 2020). "In order to examine the potential role of ER stress in colorectal cancer we determined the expression of the ER stress proteins calreticulin, calnexin, GRP78 and GRP94 in colorectal tumour and matched normal tissue from patients with Stage II (n = 8) and Stage III (n = 15) disease." (PMID 27369741, 2016). "In murine (MC38) and human (HCT116) colorectal cancer cells, CF10 induced significantly higher levels of ICD markers-extracellular ATP, HMGB1 release, and surface calreticulin-than 5-FU and triggered robust Top1cc stabilization with γ-H2AX foci formation." (PMID 42019467, 2026). "Furthermore, label-free global proteomic analysis revealed that degrader 1 induced overexpression of calreticulin (CALR), an immunogenic cell death (ICD) signaling protein known to elicit anti-tumor immune responses and clinically associated with high survival in colorectal cancer patients." (PMID 37901469, 2023). "This panel of TKIs indeed induced signs of ICD such as immunofluorescence-detectable CALR exposure and the release of ATP and HMGB1 into the culture supernatant in several human cancer cell lines (U2OS, cervical carcinoma HeLa, colorectal cancer HCT-116) and in murine fibrosarcoma MCA205 cells." (PMID 30940805, 2019). "Moreover, increased CALR expression by cancer cells has been associated with tumor infiltration by CD45RO+ memory T cells and improved 5-year overall survival amongst 68 subjects with Stage IIIB colorectal carcinoma (CRC)." (PMID 26300886, 2015).
colon carcinoma (22 papers, 2013 to 2025). "Colon cancer patients with high CALR expression are associated with a higher 5-year survival rate (43% vs. 16%) compared to those with low CALR expression." (PMID 33221760, 2020). "Calreticulin expression is usually associated with good prognosis in patients with advanced-stage colon cancer, and correlates with a proper antitumor response of the host immune system." (PMID 24225025, 2013). "Using mass spectrometry analysis, they demonstrated calreticulin exposure on the surface of CT26 mouse colon cancer cells treated with ICD inducers." (PMID 40369535, 2025). "In this study, we investigated the potential of a liposome-based nanoparticle (CRT-NP) expressing calreticulin as an in-situ vaccine to restore sensitivity to anti-CTLA4 immune checkpoint inhibitor (ICI) in CT26 colon tumors." (PMID 37376141, 2023). "Second, studies in colon cancer cells have shown that oxaliplatin can stimulate cancer cells to expose proapoptotic calreticulin (CRT), which is required for immunogenic cell death (ICD), and advocate for the effectiveness of anti-tumor therapy." (PMID 38022559, 2023). "Research found that CALR silencing prevented Epibrassinolide (EBR, a member of brassinostreoids plant hormones)-induced UPR and apoptosis in colon cancer cells, indicating that CALR inhibited EBR induced apoptosis through activating ER stress." (PMID 33209200, 2020). "CALR is reported to be served as a chaperone interacting with PDIA3 via P-domain in colon cancer cells." (PMID 29228584, 2017). "In mitoxantrone treated CT26 colon cancer cells, the translocation of calreticulin and ERp57 was accompanied by phosphorylation of PERK and its substrate eIF2α." (PMID 25688334, 2015). "Analogously, apoptotic human bladder cancer cells and murine colon cancer cells treated with the photodynamic therapeutic hypericin exposed calreticulin on their membrane." (PMID 25688334, 2015). "When treated with 5-AC, 7/8 colon cancer lines showed significant upregulation of CALR." (PMID 28622390, 2017). "Following treatment with ICD inducers (oxaliplatin and mitoxantrone), miR-27a-3p knockdown induces more cell surface CALR and HMGB1 secretion by colon cancer cells compared to that observed in cells overexpressing miR-27a-3p." (PMID 39759512, 2024). "Bleomycin, a Streptomyces verticillus-derived antibiotic, induces HMGB1, CALR, and IFNG expression in colon cancer cells." (PMID 39759512, 2024). "Similar to colon cancer, in NCSLC patients, an increase in calreticulin (CALR) along with PDIA3 predicted better prognosis." (PMID 34830970, 2021). "RB-treated colon cancer cells expressed distinct hallmarks of immunogenic cell death (ICD), including enhanced expression of calreticulin and heat-shock protein 90 on the cell surface, a decrease in intracellular ATP, and the release of HMGB1." (PMID 28151483, 2017). "The expression levels of ER stress proteins calnexin, calreticulin, GRP78 and GRP94 were determined in n = 23 Stage II and III colon cancer fresh frozen tumour and matched normal tissue samples." (PMID 27369741, 2016). "Notably, the LXR agonist T0901317 induces ICD by increasing calreticulin (CRT) and high mobility group protein (HMGB1) in colon cancer cells." (PMID 32894039, 2020). "Following exposure to oxidizing saline solutions, we identified an upregulation of key ICD-markers, such as calreticulin (CRT), heat shock protein 70 (HSP70), and high-mobility-group-protein B1 (HMGB1) on the cell surface of CT26 colon-cancer cells using flow cytometry." (PMID 30679720, 2019). "For instance, thapsigargin was found to induce an ER stress response in CT26 colon cancer cells, but failed to stimulate cellular calreticulin/ERp57 exposure." (PMID 25688334, 2015). "While one study reported that CARBO did not significantly increase ecto-CALR exposure and HMGB1 release in TSA cells (mouse mammary adenocarcinoma), another study reported its ability to induce ecto-CALR exposure and HMGB1 release in murine colon cancer cells." (PMID 32560232, 2020).
Splenomegaly (22 papers, 2016 to 2026). Abnormal increased size of the spleen. "Here we present a 69-year-old female patient with anemia and splenomegaly, exhibiting CALR exon 9 mutation (c.1099_1150del52) and JAK2 V617F negativity." (PMID 40761243, 2025). "In transplant-age patients, the presence of the CALR mutation was associated with significantly higher rates of ruxolitinib discontinuation, despite comparable degrees of splenomegaly/symptoms and reasons for ruxolitinib stop." (PMID 39831987, 2025). "The current study provides real-world observations in CALR-mutated MF patients with splenomegaly and/or symptoms requiring therapy with JAK2 inhibitors." (PMID 39831987, 2025). "In the group of patients with ET, male gender (p < 0.001), hemoglobin value > 16.5 g/dL (p < 0.001, positive CALR mutation (p < 0.001, smoking (p = 0.023), palpable splenomegaly (p = 0.001), and platelets > 450 × 109/L (p < 0.001) were predictors." (PMID 38541232, 2024). "In other data, CALR mutations in MF were signigicantly associated with longer larger splenomegaly-free survivals than others." (PMID 29562644, 2018). "And similar results regarding CALR allele burden and splenomegaly." (PMID 39960584, 2026). "Also, CALR gene mutation, male gender, platelet value, palpable splenomegaly, smoking, and hemoglobin value represent independent predictors for patients with ET." (PMID 38541232, 2024). "The prevalence of splenomegaly was comparable between JAK2- (36.8%) and CALR-mutated patients (61.1%; p = 0.19), and follow-up assessments were performed at 12 and 24 months." (PMID 41463191, 2025). "Case 2: A 73-year-old woman with a history of calreticulin (CALR, Type I 52 bp deletion)-driven essential thrombocythaemia (ET) develops marked fatigue and splenomegaly (8cm below the costal margin)." (PMID 39604140, 2024). "To explore potential determinants of engraftment, we evaluated MF disease characteristics including primary vs secondary MF, driver mutations in JAK2, CALR and MPL, prognostic risk group, splenomegaly and BM fibrosis as well as ruxolitinib therapy before HCT." (PMID 37637037, 2023). "In the 135 patients with the CALR mutation, no factors were found to be associated with spleen or symptom response, including larger splenomegaly and delayed ruxolitinib start." (PMID 39831987, 2025). "Between the time of diagnosis and the time of ruxolitinib start, clinical and hematological features worsened in both JAK2 and CALR cohorts, with progressive increase of leukocytes, blast counts, splenomegaly and symptoms, and decrease of hemoglobin levels and platelet counts." (PMID 39831987, 2025). "MF is characterized by splenomegaly, as well as severe systemic symptoms including extreme fatigue, shortness of breath, nighttime sweating, weight loss, fever, and bone pain, usually with JAK2, CALR, or MPL mutations." (PMID 40860801, 2025). "Meanwhile, the JAK2-/CALR+ group had higher rates of splenomegaly than did the JAK2-/CALR- group." (PMID 27486987, 2016). "In the data on large splenomegaly, which is defined as enlargement >10 cm from the left costal margin, CALR mutation-positive patients with MF had a significantly longer period of large splenomegaly-free survival than mutation-negative patients with MF (p < 0.001)." (PMID 29562644, 2018). "Multivariate analysis included the variable type of driver mutation (JAK2 or CALR), the detection of non-driver mutations, WBC, PLT and LDH counts, patient age, gender, left shift, splenomegaly, and fibrosis grade." (PMID 41463191, 2025). "At 24 months, splenomegaly was present in 12 of 28 patients (42.9%), again without significant differences between JAK2- and CALR-mutated cohorts (p > 0.99)." (PMID 41463191, 2025). "In our study, although numerically more splenomegaly was observed in patients with JAK2, CALR, or MPL mutations, this difference was not statistically significant." (PMID 35444868, 2022).
Splenomegaly (continued). "In the CALR-positive cohort, we could not detect any prognostic factors for spleen or symptom response, including larger splenomegaly and delayed ruxolitinib start." (PMID 39831987, 2025). "The appearance of constitutional symptoms, splenomegaly, PTL increase, RBC increase or cytopenia in patients with CML in MR should lead clinicians to rule out a coexisting Ph-negative MPN and mutations of JAK2, MPL, CALR should be evaluated." (PMID 38282677, 2023).
acute myeloid leukemia (21 papers, 2012 to 2024). Acute myeloid leukemia (AML) is a group of neoplasms arising from precursor cells committed to the myeloid cell-line differentiation. "Only one PMF patient with the CALR mutation transformed to acute myeloid leukemia after 20 years of follow-up." (PMID 34300032, 2021). "Polymerase chain reaction and direct sequencing were performed to analyze mutations of CALR in 305 patients with hematopoietic malignancies, including 135 acute myeloid leukemia patients, 57 acute lymphoblastic leukemia patients, and 113 MPN patients." (PMID 26377485, 2016). "One patient with CALR mutations had leukemic transformation to acute myeloid leukemia." (PMID 34300032, 2021). "Only one PMF patient had a CALR mutation that transformed to acute myeloid leukemia." (PMID 34300032, 2021). "However, also spontaneous release of calreticulin from acute myeloid leukemia (AML) blast was associated with eIF2α hyperphosphorylation." (PMID 25688334, 2015). "Of the 51 enrolled patients who started study medication, one patient with CALR‐mutated PMF died from transformation to acute myeloid leukemia (AML) after receiving the first dose of study medication and before reaching the 2 weeks study visit." (PMID 29932310, 2018). "CALR has been reported as a potential biomarker in several types of cancer including neuroblastoma, gastric, bladder, esophageal, breast, esophageal cancer and acute myeloid leukemia." (PMID 29228584, 2017). "An inverse relationship of C/EBPα and calreticulin had been demonstrated in adipocytes, where calreticulin inhibited adipogenesis by suppressing the expression of C/EBPα; an observation that was also reported in acute myeloid leukemia." (PMID 22500186, 2012). "The consequence of increased CALR expression in acute myeloid leukemia (AML) has been reported in a few studies." (PMID 35495123, 2022). "Moreover, CALR exposure by malignant blasts has been linked to prolonged relapse-free (but not overall) survival in a cohort of 20 individuals with acute myeloid leukemia (AML)." (PMID 26300886, 2015). "Furthermore, the median CALR allele burden remained steady over time; interestingly, differently from JAK2-positive cases, acute myeloid leukemias (AML) evolving from CALR-mutant MPNs commonly maintained their mutational profile." (PMID 31106152, 2019). "Similarly, in acute myeloid leukemia (AML) patients receiving anthracycline therapy, the ability of autologous T cells to produce an antigen-specific IFN-γ response was strongly correlated with the tumor associated ER stress (measured by phospho-eIF2α) and ecto-CALR expression." (PMID 26486085, 2015).
ovarian carcinoma (21 papers, 2014 to 2025). A malignant neoplasm originating from the surface ovarian epithelium. "The expression of CALR in primary ovarian tumors is associated with survival and response to chemotherapy in patients with ovarian cancer." (PMID 36110943, 2022). "The results can be seen to indicate that CALR may be associated with platinum resistance in ovarian cancer." (PMID 27566066, 2016). "DNMT inhibitors can play an anti-tumor role in colon and ovarian cancer by up-regulating B2M and CALR." (PMID 34910788, 2021). "Since, this paper is dedicated to calreticulin only, below we have presented the review of available data on the capacity of anti-ovarian cancer drugs to the induction of ecto-CRT on ovarian cancer cells." (PMID 33440842, 2021). "To validate these findings in a larger patient cohort, we analyzed the prognostic role of CALR mRNA levels in 302 patients with primary ovarian cancer from The Cancer Genome Atlas (TCGA) database, based on the median cutoff approach." (PMID 31747968, 2019). "CALR can activate the immune response of dying cancer cells, and the loss of CALR has proved to have a significant negative effect on the overall survival of patients with ovarian cancer." (PMID 36110943, 2022). "Firstly, the expression analyses of patients with ovarian cancer showed that the expression levels of CALR and PDIA3 in ovarian cancer were significantly up-regulated in compared with normal control tissues, while the expression of PANX1, ANXA1, HMGB1, and IFNAR1 were nonsignificant." (PMID 35991556, 2022). "In fact, recent identification of several proteins overexpressed in both PCOS and ovarian cancer, including calreticulin, fibrinogen, superoxide dismutase, and vimentin gave us a clue on the two diseases and even promising subgroup identification of ovarian cancer based on PCOS development." (PMID 32639550, 2020). "Recently a number of proteins overexpressed in both PCOS and ovarian cancer, such as superoxide dismutase, fibrinogen γ, vimentin, calreticulin, malate dehydrogenase, and lamin B2, have been identified, revealing subgroups of women with PCOS and with an increased risk of developing this malignancy." (PMID 27725832, 2016). "Identification of a number of proteins overexpressed in both PCOS and ovarian cancer, such as superoxide dismutase, calreticulin, vimentin, fibrinogen γ, lamin B2, and malate dehydrogenase, assured the identification of women with PCOS with an increased risk of developing this malignancy." (PMID 27725832, 2016). "Taxol has been shown to induce the release of DAMPs such as calreticulin, ATP and HMGB1 in ovarian cancer cells." (PMID 40369535, 2025). "Calreticulin (CRT) is an endoplasmic reticulum (ER) chaperone, but can appear surface bound on cancers cells, including ovarian cancers (OC)." (PMID 34800147, 2022). "Treatment of cancer cells with 5-AC also leads to significant re-expression of B2M, CALR, CD58, PSMB8, and PSMB9 at both the RNA and protein level in the colon and ovarian cancer cell lines." (PMID 28622390, 2017). "Secondly, the survival analyses of patients with ovarian cancer clearly indicated that the expression levels of CALR, PDIA3, ANXA1, HMGB1, IFNAR1, and PANX1 had no significant influence on overall survival (OS) and disease-free survival (DFS)." (PMID 35991556, 2022). "We confirm that treatment with DNMT inhibitors upregulates expression of the antigen processing and presentation molecules B2M, CALR, CD58, PSMB8, PSMB9 at the RNA and protein level in a wider range of colon and ovarian cancer cell lines and treatment time points than had been described previously." (PMID 28622390, 2017). "On the other hand, the stage of ovarian cancer under consideration did not change the inability of tumoural CALR expression levels in predicting the patient responses to topotecan." (PMID 26314964, 2015).
ovarian carcinoma (continued). "Moreover, OV90 ovarian cancer cells exposed to carboplatin plus paclitaxel for 24 h failed to manifest increased CALR exposure on the plasma membrane, at odds with OV90 cancer cells exposed to idarubicin (an anthracycline that triggers ICD)." (PMID 31747968, 2019).